POLR2I (RNA polymerase II subunit I)
Description:
Core component of RNA polymerase II (Pol II), a DNA-dependent RNA polymerase which synthesizes mRNA precursors and many functional non-coding RNAs using the four ribonucleoside triphosphates as substrates. Pol II is the central component of the basal RNA polymerase II transcription machinery. It is composed of mobile elements that move relative to each other. POLR2I/RPB9 is part of the upper jaw surrounding the central large cleft and thought to grab the incoming DNA template.
Synonyms: RPB9; hRPB14.5
Tractability: Small molecule: a structure with a bound ligand is known. PROTAC: ubiquitination databases record sites on it; its protein half-life has been measured.
Gene: Protein-coding gene on chromosome 19 (36,113,709 to 36,115,213, reverse strand). Ensembl gene ENSG00000105258.
Subcellular location: Nucleus, nucleolus
Subcellular location (Human Protein Atlas): Nucleoplasm
Pathways (Reactome):
Disease: Abortive elongation of HIV-1 transcript in the absence of Tat; Dengue Virus-Host Interactions; Formation of HIV elongation complex in the absence of HIV Tat; Formation of HIV-1 elongation complex containing HIV-1 Tat; Formation of the HIV-1 Early Elongation Complex; HIV Transcription Initiation; HIV elongation arrest and recovery; Pausing and recovery of HIV elongation; Pausing and recovery of Tat-mediated HIV elongation; RNA Pol II CTD phosphorylation and interaction with CE during HIV infection; RNA Polymerase II HIV Promoter Escape; Signaling by FGFR2 IIIa TM; Tat-mediated HIV elongation arrest and recovery; Tat-mediated elongation of the HIV-1 transcript; Transcription of the HIV genome; Viral Messenger RNA Synthesis
Gene expression (Transcription): Formation of RNA Pol II elongation complex; Formation of the Early Elongation Complex; MicroRNA (miRNA) biogenesis; PIWI-interacting RNA (piRNA) biogenesis; RNA Pol II CTD phosphorylation and interaction with CE; RNA Polymerase II Pre-transcription Events; RNA Polymerase II Promoter Escape; RNA Polymerase II Transcription Elongation; RNA Polymerase II Transcription Initiation; RNA Polymerase II Transcription Initiation And Promoter Clearance; RNA Polymerase II Transcription Pre-Initiation And Promoter Opening; RNA polymerase II transcribes snRNA genes; Transcriptional regulation by small RNAs
Metabolism of RNA: Processing of Capped Intron-Containing Pre-mRNA; mRNA Capping; mRNA Polyadenylation; mRNA Splicing - Major Pathway; mRNA Splicing - Minor Pathway
DNA Repair: Dual incision in TC-NER; Formation of TC-NER Pre-Incision Complex; Gap-filling DNA repair synthesis and ligation in TC-NER; Transcription-Coupled Nucleotide Excision Repair (TC-NER)
Signal Transduction: Estrogen-dependent gene expression
and 3 more pathways
Gene Ontology:
Molecular function: protein binding; DNA-directed RNA polymerase activity; zinc ion binding; nucleic acid binding
Biological process: transcription by RNA polymerase II; transcription elongation by RNA polymerase II; transcription initiation at RNA polymerase II promoter; maintenance of transcriptional fidelity during transcription elongation by RNA polymerase II; transcription-coupled nucleotide-excision repair; DNA-templated transcription
Cellular component: nucleoplasm; nucleus; RNA polymerase II, core complex; nucleolus
Genetic constraint (gnomAD): Loss-of-function variants: 15 observed, 24.45 expected, observed/expected ratio (o/e) 0.61, 90% interval 0.41 to 0.94. The upper end of that interval is the gene's LOEUF score, 0.94, which puts it in group 4 of 6, group 1 being the genes least tolerant of losing a copy. Missense variants: 120 observed, 187.37 expected, observed/expected ratio (o/e) 0.64, 90% interval 0.55 to 0.75. Synonymous variants: 72 observed, 69.93 expected, observed/expected ratio (o/e) 1.03, 90% interval 0.85 to 1.25.
Homologues: Orthologues: chimpanzee POLR2I (100% identical), guinea pig POLR2I (100% identical), macaque POLR2I (100% identical), mouse Polr2i (100% identical), pig POLR2I (100% identical), zebrafish polr2i (94% identical), dog POLR2I (89% identical), rat Polr2i (87% identical), tropical clawed frog polr2i (82% identical), Drosophila melanogaster Polr2I (74% identical), Caenorhabditis elegans rpb-9 (62% identical). Paralogues in human: POLR3K (20% identical), POLR1H (18% identical).
Diseases named in the same sentence as POLR2I in open-access papers:
POLR2I is named in the same sentence as 4 diseases in open-access papers, as found by Europe PMC text mining. Sharing a sentence is not in itself a finding about the gene and the disease. The quoted sentences say what the papers report.
atherosclerosis (1 paper, 2025). A disease characterized by the build-up of fatty material and calcium deposition in the arterial wall resulting in partial or complete occlusion of the arterial lumen. "A WGCNA approach was implemented to identify biologically meaningful gene modules highly correlated with the four key atherosclerosis‐associated RGN driver genes (i.e., AIP, DRAP1, POLR2I, and PQBP1)." (PMID 40112173, 2025).
POLR2I also shares sentences with these, for which no sentence is quoted: Huntington disease (1 paper); hypertensive nephropathy (1); tumor (1).